LAG3 (lymphocyte activating 3)
Diseases named in the same sentence as LAG3 in open-access papers (continued):
Sharing a sentence is not in itself a finding about the gene and the disease.
cancer (continued). "A point of attention should be made also in anti-LAG-3 treated cancer patients." (PMID 38322766, 2024). "Overall, LAG-3 represents a promising target in cancer immunotherapy." (PMID 39660130, 2024). "Given that LAG-3 is an early marker of exhausted T cells, treatment with anti-LAG-3 drugs might offer therapeutic benefits in cancer patients." (PMID 39406966, 2024). "As a promising therapeutic target, an in-depth understanding of the biological function and mechanism of action of LAG3 in different cancers may provide ideas for the further application and optimization of LAG3-targeted immunotherapy." (PMID 38277212, 2024). "Additionally, innovative approaches such as anti-LAG-3 ICIs, adoptive cell therapies, intratumoral immunotherapies, and cancer vaccines are under development to address drug resistance and enhance patient outcomes." (PMID 39120585, 2024). "The strategy of blocking inhibitory immune checkpoints such as cytotoxic T lymphocyte-associated protein 4 (CTLA-4), programmed cell death protein 1 (PD-1), programmed death ligand 1 (PD-L1), and lymphocyte activation gene 3 (LAG-3) has revolutionized the landscape of cancer treatment." (PMID 38632994, 2024). "Exploration of LAG-3 targeted therapies, particularly in combination with other ICIs, can potentially improve clinical outcomes, particularly among patients with refractory or advanced cancers." (PMID 39660130, 2024). "According to these results, increased expression of Gal3 and LAG3 was observed in some cancers, like UM, and could be a reason for the reduced CD8 T cell activity." (PMID 38418707, 2024). "Therefore, it is necessary to understand the relationship of LAG3 with cancer-related signaling pathways and immune pathways, including NF-κB." (PMID 38418707, 2024). "LAG3 has above all been studied in the context of a potential immunotherapeutic target for cancer." (PMID 38925457, 2024). "LAG3, a soluble lymphocyte activation gene 3 protein, is an immune checkpoint inhibitor with a strong synergistic effect with PD-1 and may be a promising cancer treatment in the future." (PMID 37359513, 2023). "The results of this study suggested that LAG3 might be a potential prognostic marker and cancer immunotherapy target." (PMID 38041068, 2023). "We utilized the cBioPortal tool to explore the genetic alterations of LAG3 in pan-cancer." (PMID 38115039, 2023). "LAG-3 is another co-inhibitory molecule on activated T-cells and other immune cells and suppresses various aspects of immune system functions (such as induction of T-cell exhaustion), which finally facilitates immune escape in the milieu of malignancies." (PMID 37264298, 2023). "The variation between the types of cancer should show a diverse role of LAG3 for cancer." (PMID 38062416, 2023). "LAG3 expression is frequently associated with exhausted T cells, and accordingly considered an exhaustion marker for CD4 + and CD8 + T cells in response to repetitive antigen stimulation in cancer." (PMID 36765348, 2023). "Furthermore, a notable heterogeneity was observed in the relationship between Eph receptors/EFN ligands and main checkpoints (CD274, PDCD1, CTLA4, and LAG3) in different types of cancer." (PMID 37637034, 2023). "LAG-3-expressing regulatory T cells exhibited an enhanced immune suppressive function, supporting the hypothesis that the presence of LAG-3 on TILs in patients with cancer leads to poor survival." (PMID 37179337, 2023). "However, the comprehensive functional analysis of LAG3 across various cancer types remains undisclosed; thus, this study aims to investigate the pan-cancer expression profile of LAG3." (PMID 38115039, 2023). "The analysis of TCGA showed a wide expression range of LAG-3 in different cancer types." (PMID 37509517, 2023). "These varying findings regarding the role of LAG3 in malignant tumors could be explained by the use of different assessment and scoring methods." (PMID 37311986, 2023).
cancer (continued). "The FGL1/LAG-3 interaction could potentially contribute to the resistance of anti-PD therapy in human cancers, and thus, FGL1 overexpression in the plasma of cancer patients is associated with poor prognosis and resistance to anti-PD-1/PD-L1 therapy." (PMID 38162657, 2023). "Furthermore, LAG3 expression was positively correlated with the infiltration of activated myeloid DCs and plasmacytoid DCs in most cancers, such as BLCA, HNSC, KIRC, OV, and UCEC." (PMID 38115039, 2023). "In addition, we also itemized the correlations between TAGLN2 and the major immune checkpoints in pan-cancer, including LAG3, PDCD1, CTLA4, CD274, and TIGIT." (PMID 37476180, 2023). "In addition to these IRs, a growing number of studies have linked the expression of inhibitory receptors such as LAG-3 and VISTA to T cell exhaustion in chronic infections and some cancers." (PMID 37355637, 2023). "LAG-3 could be another highly relevant target in feline cancers, as previous studies in humans reported a positive effect of targeting LAG-3 in association with anti-PD-1." (PMID 36672332, 2023). "Next-generation cancer immunotherapies are designed to broaden the therapeutic repertoire by targeting alternative immune inhibitory checkpoint receptors such as lymphocyte-activation gene-3 (LAG-3) and T cell immunoglobulin and mucin-domain containing-3 (TIM-3) to reinvigorate T-cell responses." (PMID 37239929, 2023). "FGL1, the ligand of LAG-3, expressed on the surface of cancer cells." (PMID 36911712, 2023). "Therefore, LAG-3 has been proposed as a promising therapeutic target for cancer immunotherapy based on results from in vitro and in vivo animal model studies." (PMID 37670328, 2023). "As of the time of this writing, there are multiple clinical trials that are investigating the role that anti-LAG-3 molecules may be able to play in the treatment of various cancers, including liver malignancies." (PMID 37174089, 2023). "Clinical trials are ongoing in other cancer types targeting LAG-3 and A2aR." (PMID 36445478, 2023). "This hypothesis has prompted the development of the anti-LAG-3 antibody, relatlimab, which is undergoing extensive evaluation in numerous randomized trials of various cancer types, including HCC." (PMID 37342338, 2023). "Our previous study showed that both adenosine derivatives, N6, N6-dimethyladenosine, CD, adenosine-inhibited DPP4/CD26 expression in cancer cells, and adenosine further revealed that it significantly suppresses the expression of the lymphocyte activating factor 3 (Lag3) in mice with AD injection." (PMID 38138098, 2023). "LAG‐3 inhibitors aim to promote effector T‐cell activity to attack cancer cells." (PMID 38047262, 2023). "Therefore, CTLA-4, PD-1, PD-L1and LAG3 inhibitors have been approved for clinical treatment in several cancer types by Food and Drug Administration (FDA)." (PMID 36911712, 2023). "Preliminary data from these trials suggest that Lag-3 inhibitors may provide clinical benefit in certain types of cancers, such as melanoma, lung cancer, and renal cell carcinoma." (PMID 37345057, 2023). "LAG3 regulates cancer immunity and is a potential target for ICIs therapy." (PMID 38062416, 2023). "Like CD4, LAG-3 is a receptor for MHC class II molecules that are present in large amounts on antigen-presenting cells but may also be aberrantly expressed by cancer cells." (PMID 37009054, 2023). "Moreover, the stage of cancer is positively correlated with the concentration of LAG-3 present in the TME." (PMID 37345111, 2023). "As of 27th February 2023, according to clinicaltrails.gov - there are 101 upcoming/ongoing clinical trials using anti-LAG3 either alone or in combination with other checkpoint inhibitors, targeted agents, or chemotherapeutic agents for various indications of cancer." (PMID 37304291, 2023). "It has been proposed that blockade of both PD-1 and LAG3 together may act synergistically to restore T cell function in cancer." (PMID 37009054, 2023).
cancer (continued). "Based on those findings, TIGIT monoclonal antibodies (such as tiragolumab, vibostolimab, ociperlimab) and multiple immune checkpoint blockade therapies (including PD-1/TIGIT, and PD-1/TIGIT/LAG-3), have all been developed for cancer treatment, and some are currently in ongoing clinical trials." (PMID 36765782, 2023). "Moreover, M1 macrophage infiltration demonstrated a positive correlation with LAG3 expression in several cancers including BLCA, HNSC, KIRC, READ, OV, SKCM and UCEC." (PMID 38115039, 2023). "Reinvigoration of T cells has been the major goal of monoclonal antibodies against TIM-3, LAG-3 and PD-L1/L2, but NK cells may be also rescued by their inhibition in the cancer microenvironment." (PMID 38090565, 2023). "LAG3-LGALS3 interaction inhibits T cell responses promoting cancer progression." (PMID 37215135, 2023). "Immune checkpoint blockade in T cells using antibodies that target cytotoxic T-lymphocyte-associated protein 4 (CTLA-4), programmed cell death protein 1 (PD-1) or its ligand PD-L1, and more recently lymphocyte-activation gene 3 (LAG3) has proven therapeutic efficacy in different cancer types." (PMID 37781391, 2023). "Based on the TCGA database, we investigated the expression of LAG3 in 33 cancers." (PMID 38115039, 2023). "Although we did not observe higher expression of markers associated with effector cells in the ‘surrounding stromal leukocyte’ regions cf. ‘immune-rich cancer cell islet’ regions, we did observe higher expression of IC markers such as LAG3, Tim-3 (HAVCR2), VISTA, and PD-L1 in the surrounding stroma." (PMID 37046826, 2023). "Numerous trials assessing LAG-3 across different cancer indications and in combinations could change the existing strategy for immunotherapies." (PMID 37427115, 2023). "Given its likely role in the immunopathogenesis of cancer, the anti-LAG-3 antibody relatlimab has also recently received approval for metastatic melanoma, and clinical trials investigating relatlimab in conjunction with other ICIs in various cancers are currently underway." (PMID 36672615, 2023). "Immune checkpoints are also important targets in cancer immunotherapy, such as lymphocyte-activation gene-3 (LAG-3), T cell immunoglobulin and ITIM domain (TIGIT), V-domain Ig suppressor of T cell activation (VISTA), and T cell immunoglobulin and mucin-domain containing-3 (TIM-3)." (PMID 38136311, 2023). "It is worth noting that combining LAG3 with other biomarkers may improve prognosis and treatment response prediction in patients with cancer." (PMID 38041068, 2023). "In addition, LAG-3 regulates a diversity of biological mechanisms and its use as a cancer target keeps on holding relatively high promises." (PMID 35755891, 2022). "Importantly, answering the questions which shroud LAG-3 in mystery will allow the maximum therapeutic benefit of LAG-3 targeting immunotherapies in cancer, autoimmunity and beyond." (PMID 35265944, 2022). "In addition to CTLA-4– and PD-1/PD-L1–targeted cancer immunotherapy, LAG3 (lymphocyte activation gene-3, CD223) is the third clinically targeted inhibitory receptor." (PMID 35651784, 2022). "Notably, many ongoing clinical trials are attempting to assess the application of TIGIT blockade or TIGIT blockade in combination with anti-PD-1/PD-L1, anti-CTLA-4 or anti-LAG-3 antibodies in the treatments for many cancers." (PMID 35320940, 2022). "Similar to the pan-cancer analysis, LRP2 mutations had high TMB, MSI and immune cell infiltration in EC and also leaded to high expression of immune-related genes, such as CXCL9, CXCR6, CXCL13, ICOS and immune checkpoint genes (CTLA4 and LAG3)." (PMID 35834061, 2022). "If these problems could be solved, the research on LAG-3 and its related drugs will make significant progress for cancer therapy." (PMID 35958563, 2022). "LAG-3/MHC-II binding complex has shown to play key roles in cancer immune escape." (PMID 36059606, 2022). "In many cancers, the combination of LAG3 and PD-1 inhibition has been synergic." (PMID 35434132, 2022).
cancer (continued). "A separate important group in which LAG-3 plays a role in cancers." (PMID 36359346, 2022). "PD-1, PD-L1, CTLA-4, and LAG-3 are currently approved therapeutical targets in cancer therapy." (PMID 36263134, 2022). "Soluble Lag3 has also been shown in cancer studies to activate antigen-presenting cells." (PMID 36558958, 2022). "The discovery of immunotherapy via the LAG3/FGL1 axis represents a milestone in cancer treatment." (PMID 34975333, 2022). "However, cancer cells can generate suppressive factors including lymphocyte-activation gene 3 (LAG-3), TGF-β, prostaglandin E2 and IL-10 that inhibit immune response, thus escaping detection and clearance by the immune system." (PMID 35844558, 2022). "Notably, CD274/PD-L1, PDCD1LG2/PD-L2, PDCD1/PD1, cytotoxic T lymphocyte-associated antigen 4 (CTLA4), T cell membrane protein 3 (TIM3; also known as HAVCR2), and lymphocyte activation gene 3 (LAG3) were correlated to FAM72A across different cancers." (PMID 36613817, 2022). "However, the molecular mechanism of how LAG3 affects the T cell function in the scenario of cancer still remains to be illustrated." (PMID 36180876, 2022). "As the first anti-LAG3 human IgG4 monoclonal antibody and novel immune checkpoint inhibitor, relatlimab, discovered by Bristol-Myers Squibb, is currently undergoing 46 different clinical trials for cancer therapy." (PMID 35958563, 2022). "Elevated levels of FGL-1 in cancer may contribute to suppression of activated T cells and evasion of antitumor immunity, however, relative contributions of disrupting LAG-3 interactions with FGL-1 or MHC-II in patients is unclear." (PMID 35217575, 2022). "Together, the FGL1/LAG3 and PD-1/PD-L1 axes might be independently targeted in treating cancers though synergism of the two yields better therapeutic outcomes." (PMID 34975333, 2022). "Therefore, the available preclinical and clinical data indicate that LAG-3 inhibition holds promise for stimulating the immune response to cancer, especially in combination with anti-PD-L1." (PMID 36140182, 2022). "Especially, high expression of LAG3, CTLA4, PDCD1 (PD-1), IDO1, and CD274 (PD-L1) were widely reported to be associated with suppressive immune response and suppressed T cell function in cancer." (PMID 35902970, 2022). "In addition, 10 different LAG3-specific monoclonal antibodies and six bispecific antibodies are currently under investigation at various clinical stages for the treatment of cancer." (PMID 35958563, 2022). "LAG-3 is a potentially effective target for cancer treatment." (PMID 36016257, 2022). "Remarkably, LAG3 is considered another promising target for cancer therapy." (PMID 35479513, 2022). "IMP321 was the first anti-cancer drug targeting LAG-3 to enter clinical trials." (PMID 34454491, 2021). "Moreover, insistent stimulation of antigen, like chronic viral infection and cancer, leads to increased levels of chronic LAG3 expression, which results in T cell exhaustion and consequent diminishing of T cell function." (PMID 33918146, 2021). "Lymphocyte activation gene-3 (LAG-3) is also a promising target for cancer immunotherapy." (PMID 34064410, 2021). "The expression of LAG-3 can be elevated on exhausted T cells in cancer." (PMID 34917131, 2021). "Therefore, FGL1 can be identified as a next-generation cancer immunotherapy target capable of a functional interaction with the LAG3 pathway and synergistic inhibition of T cells with PD-1." (PMID 34526102, 2021). "FGL1 and LAG-3 are closely related to the prognosis and clinicopathological features of various types of cancer, and clinical studies have shown that dual FGL1/LAG-3 and PD-1/PD-L1 blockade therapy has promising survival benefits and long-duration response rates." (PMID 33633363, 2021). "These luminal B cancers exhibited higher activity of pathways associated with the ECM-regulated Hippo pathway and immune tolerance, including mRNAs encoding checkpoint inhibitor molecules (IDO1, PD1, LAG3) and increased IFNγ-STAT1 signaling." (PMID 34359625, 2021).
cancer (continued). "Although dexamethasone has been shown to promote the downregulation of LAG-3 expression on T cells, the effect of steroids in cancer patients receiving ICI treatment may be exceptional." (PMID 34442054, 2021). "Whether LAG-3-mediated regulation of NKT cells is of critical importance in cancer immunity remains to be elucidated." (PMID 34572874, 2021). "TIM‐3 (p = 0.003), LAG‐3 (p = 0.007) and PD‐1 (p = 0.002) stromal immune cell expression, as well as tumoural PD‐1 (p = 0.049) and CICSS (p < 0.001) were significantly associated with cancer‐specific survival." (PMID 33338327, 2021). "The immune checkpoint receptor LAG-3 has emerged as a target for the treatment of cancer patients." (PMID 34727262, 2021). "PDCD1, CTLA4, TIM3, TIGIT, and LAG3 play key roles in the immune evasion of cancer cells." (PMID 34844217, 2021). "LAG-3 is evaluated in various types of cancer and has a synergistic effect with PD-1/PD-L1 axis." (PMID 34691076, 2021). "Meanwhile, Siglec15 was positively related to PD-L1, PD-1, CTLA-4, and LAG-3 in most cancers." (PMID 33537076, 2021). "Collectively, drugs acting on the pathways of either LAG3/MHC II or LAG3/FGL1 could play a role in the cancer therapy." (PMID 33146865, 2021). "Furthermore, LAG-3 and Tim-3 have both gained substantial interest in adult cancer therapy leading to multiple anti-LAG-3 and anti-Tim-3 clinical trials (NCT01968109, NCT02817633)." (PMID 35938052, 2021). "We further explored the correlation between YTHDC2 and eight immune checkpoint‐related genes and found that YTHDC2 was significantly associated with the expression of SIGLEC15, IDO1, CD274, HAVCR2, PDCD1, CTLA4, LAG3 or PDCD1LG2 in almost all types of cancers except for CESC and TGCT." (PMID 34312987, 2021). "In addition, the 5mC score was negatively correlated with the expression of four critical immune checkpoints, PD-L1, PD-1, CTLA-4, and LAG-3, in most cancers." (PMID 34836536, 2021). "Similarly, other checkpoints, including TIM-3, BTLA, and LAG-3, are under active investigation as potential biomarkers for cancer theranostics." (PMID 34940257, 2021). "The checkpoint receptor LAG-3 holds great potential in cancer immunotherapy." (PMID 31974523, 2020). "How modulation of LAG-3 expression on T cells could impact cancer immunotherapy approaches is worthy of further investigation." (PMID 32299365, 2020). "Although the function of s-LAG3 is unclear, several studies suggest s-LAG3 might be a valuable circulating biomarker for cancer prognosis." (PMID 33488573, 2020). "The role of LAG3 has been extensively investigated in several human cancers, whereas until recently, the role of LAG3 in the central nervous system (CNS) has been largely unknown." (PMID 32340360, 2020). "However, immune-competent subtypes in several cancer types had relatively lower expressions than immune-deficient subtypes, particularly VTCN1 in GBM and LAG3 and IDO1 in PCPG were significantly elevated in immune-deficient subtypes." (PMID 32533054, 2020). "Particularly, CD48, HAVCR2, LAG3, and TIGIT were identified as novel immunotherapeutic targets of several cancers, suggesting that the low-risk OS patients might benefit from their candidate inhibitors." (PMID 32908905, 2020). "However, it is certain that LAG-3 shows a remarkable synergy with PD-1 in promoting immune escape of cancer cells." (PMID 33374804, 2020). "Several clinical trials have investigated LAG3-targeting molecules mainly in cancer immunotherapy." (PMID 32340360, 2020). "A recent meta-analysis of 15 studies investigated the prognostic value of LAG3 in cancer." (PMID 32861198, 2020). "Both CTLA4 and LAG3 have been considered as the immune checkpoint targets in cancer immunotherapy." (PMID 33457419, 2020).